RNU6-1170P (RNA, U6 small nuclear 1170, pseudogene)
Gene: Small nuclear RNA gene on chromosome 10 (42,605,158 to 42,605,263, forward strand). Ensembl gene ENSG00000251783.
Homologues: Orthologues: chimpanzee U6 (97% identical), macaque U6 (85% identical), guinea pig U6 (67% identical), mouse Gm23535 (61% identical), rat LOC120096464 (54% identical). Paralogues in human: RNU6-795P (90% identical), RNU6-315P (75% identical), RNU6-1013P (75% identical), RNU6-1287P (75% identical), RNU6-552P (75% identical), RNU6-668P (75% identical), RNU6-1084P (74% identical), RNU6-1209P (74% identical), RNU6-128P (74% identical), RNU6-209P (74% identical), RNU6-21P (74% identical), RNU6-411P (74% identical), and 1288 more.